CD4 (CD4 molecule)
Diseases named in the same sentence as CD4 in open-access papers (continued):
Sharing a sentence is not in itself a finding about the gene and the disease.
infection (continued). "Intriguingly, KLRG-1 expression was almost entirely restricted to the effector CD4+ T-bet+ population and very few T-bet−effector CD4+ T cells expressed KLRG-1 in either WT or WSX-1−/− mice on day 14 of infection." (PMID 23593003, 2013). "Efficacy against infection in volunteers with the highest category of anti-CSP antibody titres and of CSP-specific CD4+ T cells is estimated to be 79% (95% CI, 58%–89%)." (PMID 23613845, 2013). "At 8 days post-infection, the expression of CD44 and CD25 by GranzymeB+CD4+ T cells was strongly decreased, whereas IFN-γ production persisted." (PMID 24367519, 2013). "For this analysis, time from infection to diagnosis was set as a fixed factor and the model was run for 35% and 75% of DTS efficiency and for 200, 350 and 500 cells/μl treatment CD4 thresholds." (PMID 23308161, 2013). "In conclusion, we demonstrate here that a month after infection, a single CCR5-restricted viral cluster massively and broadly spreads among all resting CD4 T-cell subsets, including naive cells." (PMID 23691172, 2013). "However, infection of mice with Helicobacter can yield both a resistant (low bacterial load, severe pathology, extensive CD4+ T cell infiltration, high IFN-γ) and a tolerant phenotype, so inbred mice may in fact be more genetically diverse than is usually thought." (PMID 23468628, 2013). "Triple-positive polyfunctional CD4+ T cells were evaluated in the spleen, and although Mtb induced increases in spleen CD4+IFN-γ+ and CD4+IL2+ cells, the infection significantly reduced the frequencies of triple-positive CD4+TNF-α+IFN-γ+ cells." (PMID 24250805, 2013). "Infection of NK cells by HIV-1 has been controversial, but accumulating data support that a CD4-expressing NK cell subset is permissive for HIV-1 replication." (PMID 24278768, 2013). "The enriched CD4+ populations were infected at an MOI of 10 in mono- and dual-infections, a multiplicity sufficient to ensure production of fluorescent cells for fitness calculations without generation of co-infected cells (dually fluorescent)." (PMID 23638182, 2013). "Cis- and trans-infection processes of R5- and X4-tropic HIV-1 from DCs to CD4+ T cells are two dissociable events differently affected by the maturation state of DCs." (PMID 23844079, 2013). "Our results show that pDC were largely reduced in the DLN of DT-treated mice on day 7 p.i. suggesting their absence throughout the course of infection and that absolute numbers of CD8 and CD4 T cells in DLN were comparable between PBS and DT-treated mice." (PMID 24204273, 2013). "The previous experiments clearly demonstrated that HCMV lytic infection of MHC Class II positive dendritic cells lead to antigen presentation of both UL138 and LUNA peptides and subsequent CD4+ T cell recognition." (PMID 24130479, 2013). "Infection with HIV, which gradually destroys the CD4 lymphocytes and other immune system cells that provide protection from life-threatening infections, is usually diagnosed by looking for antibodies to HIV in the blood or saliva." (PMID 23966838, 2013). "GRFT inhibited HIV-1(IIIB) infection of CEM and HIV-1(NL4.3) infection of C8166 CD4+ T-lymphocytes at an EC50 of 0.059 and 0.444 nM, respectively." (PMID 23741304, 2013). "Virus-specific proliferative CD4 and CD8 T-cell responses, important for the control of infection, are observed in some HIV-1+ patients during early stages of disease, and are maintained in long-term non-progressing subjects." (PMID 23459797, 2013). "And our results showed that the levels of IFN-γ and the percentages of both IFN-γ+CD4+ and IFN-γ+CD8+ T cells in group 1 (rL H5-H1N1) and group 2 (rL H5 + IL-2-H1N1) increased significantly after infection." (PMID 24053449, 2013). "Despite the high degree of CD4+ T-cell depletion in semen, SIV DNA was detected in these cells at all stages of infection." (PMID 24348253, 2013).
infection (continued). "At eight weeks post infection, the percentages of CD4+ IFN-γ+ and of CD4+ IL-4+ T cells were also similar, whereas the percentage of CD4+ IL-10+ T cells was significantly lower in Linb-11-immunized mice." (PMID 23717705, 2013). "RRV infection significantly decreased the numbers of CD4 SP, DP and DN thymocytes in NOD mice at day 21 post infection (p≤0.020), and CD8 SP cells showed a possible trend for reduced numbers (p = 0.064)." (PMID 23554993, 2013). "It appears that pDC are less permissive for productive, cis infection with HIV-1 than are myeloid DC, even though they both express CD4 and HIV-1 coreceptors." (PMID 24278768, 2013). "When diagnosis is achieved later than four years after infection, undiagnosed HIV positive individuals with CD4 counts lower than 250 or 350 cells/μl starts to become an increasing proportion of the total undiagnosed population." (PMID 23308161, 2013). "The importance of the density of CD4 and of HIV CCR5 co-receptor expression for efficient infection has been also investigated in other cells different from human CD4+ T cells." (PMID 23634877, 2013). "During infection with LAI, CD4+ T cell levels in blood were dramatically reduced while CD4+ T cells in the blood of uninfected mice were maintained at approximately 80% of total blood T cells." (PMID 24172637, 2013). "The molecular mechanisms involved in CD4+ T-cell killing by HIV infection have been studied in great detail, leading to novel insights into the down-stream effects of abortive infection and viral integration on cell death." (PMID 24133492, 2013). "LC purified from migrating cells of human epidermis explants express CD4, the primary receptor for HIV-1, and coreceptor CCR5, which is required for infection by R5 tropic strains of HIV-1." (PMID 24278768, 2013). "In patients that naturally control viral replication, both HIV-specific CD4+ and CD8+ T-cell responders are readily detectable and maintained throughout infection." (PMID 24287598, 2013). "DN T cells are refractory to SIV-infection, which likely aids their ability to maintain function and proliferative capacity during SIV infection and the subsequent CD4 depletion observed in the CD4-low mangabeys." (PMID 23825945, 2013). "On the contrary, binding of ICAM-1 to LFA-1 is necessary for both the interaction between mDC and primary CD4+ T cells and efficient mDC-mediated HIV-1 trans-infection." (PMID 23590845, 2013). "By 5 weeks post infection we observed destruction of the infected ear in RAG+CD8 mice, but minimal pathology in either Rag1−/− or RAG+CD4+CD8 mice." (PMID 23874205, 2013). "In early infection the CSF HIV population is generally similar to that of blood and likely reflects origin in the meninges, production by trafficking CD4+ T cells and exhibiting T cell tropism." (PMID 23943280, 2013). "PD-1–CD160 co-expression was also greater on the CD8+ than the CD4+ T cells of mice in the “PD1-HI” and control groups considered together, but only at the later time point of 26 weeks post infection." (PMID 24204962, 2013). "We also observed greater frequencies of CD4 and CD8 T cells in the BAL fluid and blood samples that were both CD38+ and Ki67+ during the acute m3KOΔnef infection phase than in those animals infected with SIVmac239Δnef." (PMID 23785211, 2013). "A/J mice inoculated intratracheally with L. pneumophila showed an increased number of circulating CD4+ and CD8+ T-cells in the second phase of infection when circulating cytokine levels and bacterial counts already declined." (PMID 23646123, 2013). "Thus while infection with the clonal virus appeared to induce a transient increase in CD8+ lymphocytes and significant reduction in CD4+ lymphocytes, infection with the mixture of viral variants induced a sustained increase in CD8+ lymphocytes and a more modest reduction in CD4+ lymphocytes." (PMID 23372784, 2013).
infection (continued). "Thus, accumulation of pre-existing influenza virus-specific immunity in the form of NAb and cross-reactive T cells to conserved virus proteins (e.g. NP and M) over a lifetime of exposure to infection and vaccination may influence vaccine-induced CD4 T cell responses in the aged." (PMID 24155927, 2013). "We have demonstrated that C. crescentus displaying MIP1α or CD4 interfered with the virus entry pathway and provided significant protection from HIV-1 pseudovirus representing clade B in a standard single cycle infection assay." (PMID 23840383, 2013). "Mean percentages ± SD of CD4+, CD8+ or CD19+ cells producing IFN-γ or IL-17 in 129 Sv/Ev or IL-10 KO splenocytes at one week post-infection with Brucella abortus." (PMID 24069337, 2013). "In the macaque studies, ART control of acute viraemia was induced 3 weeks post infection, thereby preserving a healthy CD4+ T-cell pool, including fresh primed SIV specific CD4+ and CD8+ T-cell responses." (PMID 24124451, 2013). "Median duration since HIV diagnosis was 3.8 months (IQR: 1.5–7.1), median HIV-1 RNA level was 4.6 log10 copies/mL (IQR: 4.1–5.2), median CD4+ T-cell count was 300/mm3 (IQR: 173–463) and 34 patients (9.6%) were at CDC stage C of infection." (PMID 24058636, 2013). "As it is generally accepted that infected CD4 T cells harbor only one HIV-DNA molecule, we can extrapolate the numbers of infected cells from the measured infection levels." (PMID 23691172, 2013). "Together, these processes increase the probability of HIV-1 Env-CD4/co-receptor interactions, potentiating fusion pore formation and hence, HIV-1 viral fusion and infection." (PMID 23575248, 2013). "In contrast, effector CD4+ T-bet+ T cells from WSX-1−/− mice on days 9 and 14 of infection were hyperresponsive to both rIL-12p70 and rIL-2, and significantly upregulated pSTAT4 and pSTAT5 respectively following in vitro stimulation." (PMID 23593003, 2013). "Recent work identified SAMHD1 as the protein that blocks infection of SIV∆Vpx, HIV-2∆Vpx and HIV-1 before reverse transcription in macrophages, dendritic cells and resting CD4+ T cells." (PMID 24219908, 2013). "In contrast, many T cells including primary human CD4+ T cells are poorly permissive to cell-free HIV, which effectively blocks the cell-free mode of infection and promotes a target cell-induced contact-dependent mode of spreading." (PMID 23308151, 2013). "The BALB/c mice exhibited increased spleen cell indexes as follows: F4/80+ at 100 days after infection (DPI), CD4+ at 100 and 250 DPI, CD8+ at 35 and 100 DPI, and CD19+ at 100, 150, and 250 DPI." (PMID 27335846, 2013). "The expression of CD44 and CD40L in the CD4+ and CD8+ T cells was gradually up-regulated post-infection, while the expression of CD62L was down-regulated (middle and lower)." (PMID 23555767, 2013). "This suggested a second pathway to the CD4/CCR5 receptor, productive infection, where LC capture HIV-1 by other receptors and transmit the virus to T cells." (PMID 24278768, 2013). "CD4+ T cells removed from anti-CCL5- and TAK779-treated mice also exhibited unimpaired migration to infection-derived liver cells when placed in a transwell assay in vitro." (PMID 24244314, 2013). "For Ad.IL5 and Ad.IL23, this improvement correlated with enhanced neutralizing antibody titers after FV challenge infection, whereas mice co-immunized with Ad.IL6 showed improved virus-specific CD4+ T cells." (PMID 24349306, 2013). "Total and activated CD4+ and CD8+ T cell number in BAL and lung tissue were also significantly increased compared to infection or immunization treatments alone." (PMID 24086140, 2013). "During primary infection, HIV-1 in mucosal tissue is first internalized by DCs, which then migrate to secondary lymphoid organs, where the virus is transferred to CD4+ T lymphocytes (CD4TL)." (PMID 23874461, 2013).
infection (continued). "We are currently examining the relative importance of CD4+ T cell intrinsic and extrinsic WSX-1 signalling in limiting the IL-12 pathway, and hence Th1 cell differentiation, in vivo during infection." (PMID 23593003, 2013). "Splenic CD4+ and CD8+ T cells expressing CD69 were increased in response to infection with PyL in WT mice." (PMID 23527234, 2013). "This is followed by recruitment of helper CD4+ and cytotoxic CD8+ lymphocytes to the site of infection." (PMID 23947615, 2013). "The model developed by Lewin and colleagues uses exposure of primary resting CD4+ T cells to chemokines that bind to receptors CCR7, CXCR3 or CCR6 to effectively establish infection with wild-type NL4-3 virus." (PMID 24385908, 2013). "CD134 was first described as a surface antigen that was expressed almost exclusively on CD4+ T cells, thus the extended tropism of FIV during the course of infection would seem counter-intuitive." (PMID 23992667, 2013). "HSV-2 infection of Fas and FasL- deficient mice led to decreased apoptosis of monocytes and impaired recruitment of NK, CD4+ and CD8+ T cells within the infection sites." (PMID 23922974, 2013). "The Mochudi-unique cluster #125 with 11 members contained predominantly young females with one incident infection, a broad range of HIV-1 RNA load, CD4 counts between the mid-200s and mid-500s, and 3 individuals on ART." (PMID 24349005, 2013). "CD4+ T cell and CD8αβ TCRαβ T cell numbers increased over controls in the MLN of NOD mice at day 2 post infection (p = 0.0017 and p = 0.0025, respectively)." (PMID 23554993, 2013). "Characterization of this mouse revealed that it has normal expansion of CD4+ and CD8+ T cells, and produces normal levels of IL-12 and IFN-γ following infection with T. gondii." (PMID 23633952, 2013). "However, the intrinsic fate of parasite-specific CD4+ Th2 cells within a chronic down-regulatory environment is largely unknown, even though the idea that helminth-elicited T cells become anergised during infection was postulated 20 years ago." (PMID 23516361, 2013). "In agreement with previous studies we demonstrate here that DCs, B cells, macrophages, CD4+ and CD8+ T cells, but also neutrophils, NK cells and NKT cells produce IL-10 in the early phase of high dose LCMV Clone 13 infection." (PMID 24244162, 2013). "Similar results were obtained with CD4+ T-cells, where median HIV-1 gag-p24 antigen release in their supernatants at 7 days post infection (compared to HIV-1BaL) was 62.9% (50,831 pg/ml; IQR: 10,146–92,302 pg/ml; 12 isolates tested) (data not shown)." (PMID 23874501, 2013). "To evaluate this possibility, we enumerated CD4+ and CD8+T cells, as well as IFN-γ+ cells in the brains of P. berghei ANKA-infected WT and Alox5−/− mice 5 days after infection." (PMID 23613965, 2013). "Since the T. cruzi lysate has proved to mainly induce CD4+ T cell responses and to a much lesser extent CD8+ T cell responses in chronic T. cruzi-infections, we focused on CD4+ T cell responses for flow cytometry assays." (PMID 24349591, 2013). "During the third phase from day 5 until day 15 post-infection, transcriptional regulators STAT1 and STAT3 are highly expressed, together with IFNγ characteristic of CD4 T-lymphocyte activity." (PMID 23687968, 2013). "During the course of low dose infection, both, C57BL/6 and IL-22−/− mice generated similar frequencies of Mtb-specific TH1 and TH17 cells within the CD4+ cell population and within total lung cell suspensions." (PMID 23460846, 2013). "Interestingly, the increase in TGFβ signalling observed in CD4+ T-cells early during T.muris infection was significantly reduced in Itgb8 (CD11c-Cre) mice, with pSmad2/3 levels remaining similar to those observed in uninfected mice during the first week of infection." (PMID 24098124, 2013). "This confirms the critical role of the lack of immediate-early IFN-α burst in the shaping of CD8+ and CD4+ T cell responses and in the protracted fate of LCMV-WE infection in early life." (PMID 24376875, 2013).
infection (continued). "Furthermore, T cells were the only cell population to fully restore resistance to HSV-1 in the mutants, an effect that required both the CD4+ and CD8+ T cells and could be attributed to function of CD4+ T helper 1 (Th1) cells in CD8+ T cell recruitment to the site of infection." (PMID 24068938, 2013). "Thus, to test whether protection from infection in Itgb8 (CD11c-Cre) mice could be due to deletion of the integrin in T-cell subsets, we infected mice lacking integrin αvβ8 on T-cells via expression of CD4-Cre (Itgb8 (CD4-Cre) mice)." (PMID 24098124, 2013). "Taking a closer look at CD4+ T cell subsets following infection in the wild-type model, we observed that in the GLN, Th1 cells peaked on day 30 post infection and remained at high levels with fairly constant values throughout the rest of the infection period." (PMID 24039925, 2013). "To identify the soluble, WSX-1-regulated liver-derived signal(s) that control CD4+ T cell migration, we first compared the repertoire and levels of chemokine production in livers from WT and WSX-1−/− mice on day 7 and day 14 of infection." (PMID 24244314, 2013). "However, recent data suggests that CD4-DN-TGFβRII mice display high levels of IFNγ level during intestinal helminth infection which, given the known role of IFNγ in promoting chronic T. muris infection, may explain the enhanced levels of infection observed in CD4-DN-TGFβRII mice." (PMID 24098124, 2013). "Of significance is that trans infection from mature DC to T cells is dependent on levels of CD4, as blocking CD4 on immature MDDC enhances their trans infection with X4 virus." (PMID 24278768, 2013). "Briefly, CD4+ T cells were stimulated for 72 h and subsequently magnetofectedTM with HIV-1BaL for 48 h, yielding an average infection across seven experiments of 54.8%." (PMID 24040353, 2013). "Percentages and absolute numbers of splenic effector CD4+ T-bet+ T cells increased at a similar rate in WT and WSX-1−/− mice until day 9 of infection." (PMID 23593003, 2013). "Both the primary and secondary CD4 T cell responses peaked at day 8 post-LCMV infection, then contracted and formed memory populations that were easily detectable at 4 months post-infection." (PMID 23762323, 2013). "Very few effector CD4+ T-bet+ T cells expressed KLRG-1 in either WT or WSX-1−/− mice on days 0, 7 and 9 of infection." (PMID 23593003, 2013). "We found a large increase in CXCR3 populations of both CD4+ and CD8+ T lymphocytes in MLN, spleen (SPL) and LP compartments following infection." (PMID 24130498, 2013). "On day 5 post infection around 6% of the NK cells and 0.4–2% of the NKT cells, DCs, CD4+ and CD8+ T cells were GFP+." (PMID 24244162, 2013). "Lamina propria CD4+ T cells are under a steady state of activation and express the primary CD4 receptor and CCR5 and α4β7 coreceptors, making them fertile ground for either cis or trans infection." (PMID 24278768, 2013). "At day 7 p.i., however, the frequency of CD8+ T cells raised to 50% in equal proportions to CD4+ T cells, indicating CD8+ T cell recruitment to the site of infection." (PMID 24068938, 2013). "In our studies, we found that CD4+ (Foxp3+ and Foxp3−) and CD8+ T cells, along with some NK cells and myeloid cells (CD11b+), were the major IL-10 producers early after infection." (PMID 23555256, 2013). "Given that CD4+ and CD8+ T cells are a source of IL-21, expression of this cytokine by these populations in the spleen and brain was examined after infection." (PMID 23667536, 2013). "On the contrary, the main driving force behind formation of mDC-CD4+ T-cell conjugates and HIV-1 trans-infection of CD4+ T cells was the interaction between ICAM-1 and LFA-1." (PMID 23590845, 2013). "The existence of a highly protected subgroup of volunteers suggests that efficacy against infection in excess of 70% is possible if both anti-CSP antibody titres and numbers of CSP-specific CD4+ T cells can be boosted to high enough levels." (PMID 23613845, 2013).